CXCR3 (C-X-C motif chemokine receptor 3)
Diseases named in the same sentence as CXCR3 in open-access papers (continued):
Sharing a sentence is not in itself a finding about the gene and the disease.
type 1 diabetes (continued). "In line with previous studies, we found reduced expression levels of CXCR3 on circulating CD3+ T cells in individuals with type 1 diabetes." (PMID 29881878, 2018). "Direct comparisons are required to fully understand whether there are differences in CXCR3 dynamics between individuals with young- vs adult-onset type 1 diabetes, to fully determine whether CXCR3 is required for B cells to migrate to the pancreas." (PMID 41273416, 2026). "Furthermore, the chemokines CXCL10 and CXCL11 (ligands for CXCR3) are elevated in the serum of individuals with type 1 diabetes." (PMID 41273416, 2026). "We sought to understand whether B cells from individuals with type 1 diabetes also show an overall reduction in response to IFNγ, an inflammatory cytokine that upregulates CXCR3 expression." (PMID 41273416, 2026). "Moreover, we also show an increase in CXCR3 expression on CD20+CD8+ T cells in the peripheral blood of adult RO type 1 diabetes." (PMID 41273416, 2026). "We treated isolated B cells with IFNγ for 5 days, and found increased CXCR3 expression compared with unstimulated cultures in ND donors and individuals with type 1 diabetes, whether RO or LD." (PMID 41273416, 2026). "In this study, we investigated CXCR3 responses in B cells during type 1 diabetes progression." (PMID 41273416, 2026). "In this study, we investigated the imbalanced CXCR3 expression on B cells in type 1 diabetes." (PMID 41273416, 2026). "This makes CXCR3 a potential therapeutic target, and blocking CXCR3 may slow or prevent the development of type 1 diabetes." (PMID 40786052, 2025). "Moreover, CXCL9, in conjunction with CXCL10, also changes the mass and function of β-cells, and deletion of CXCR3 in mice delays the onset of type 1 diabetes." (PMID 40597598, 2025). "Similarly, an effector memory Treg subset expressing HLA-DR, CCR4, CCR6, CXCR3, and GATA3 was increased in the high-risk group of patients with type 1 diabetes." (PMID 37189479, 2023). "In the present study, the combination of ACT-777991, a new, potent, insurmountable, and selective small molecule CXCR3 antagonist, with aCD3 demonstrated superior efficacy over each monotherapy in persistently reverting diabetes in two different type 1 diabetes mouse models." (PMID 37458220, 2023). "Even if CXCR3 was shown to be increased on various T-cell subsets in patients with type 1 diabetes, thus potentially having a detrimental effect on disease progression, some studies have reported reduced CXCR3 expression on blood T cells in individuals with long-lasting type 1 diabetes." (PMID 37458220, 2023). "Decreased expression levels of CXCR3 on memory B cells in individuals with type 1 diabetes may therefore reflect ligand-induced receptor internalisation and/or downregulation." (PMID 29881878, 2018). "Indeed, a recent study showed that CXCR3+T-bet+ Treg cells are essential for control of type 1 diabetes." (PMID 29951069, 2018). "We previously showed that expression of C-X-C chemokine receptor type 3 (CXCR3), a chemokine receptor that is widely expressed on T cells and on antigen-experienced B cells, is notably reduced on peripheral blood lymphocytes from individuals with long-duration (LD) type 1 diabetes." (PMID 41273416, 2026). "Most recently, it has been shown that CXCR3 gene expression on stem-like CD8 T cells in pancreatic lymph nodes is increased in autoantibody-positive individuals and those with type 1 diabetes." (PMID 41273416, 2026). "IL-10 downregulates CXCR3 expression on CD4+ Th1 cells, and expression of this cytokine has been shown to be elevated in individuals with type 1 diabetes, specifically those who are older at onset." (PMID 41273416, 2026). "However, as fewer B cells are present in the pancreas in adult-onset type 1 diabetes, comparisons of CXCR3 expression in the pancreas of those who are older at diabetes onset with CXCR3 expression in young-onset disease may be challenging due to the limited number of cells available to study." (PMID 41273416, 2026).
type 1 diabetes (continued). "In type 1 diabetes, insulin-specific autoreactive B cells have increased CXCR3 expression compared with non-insulin binding B cells, and are enriched in the pancreatic lymph nodes of individuals with type 1 diabetes." (PMID 41273416, 2026). "T-bet- dependent CXCR3+ Tregs accumulated within the pancreatic islets (but not the spleen) in the NOD mouse model of type 1 diabetes, at a frequency that correlated inversely with the size of the inflammatory infiltrate." (PMID 36993956, 2023). "We next wished to clarify whether the reduction of CXCR3 expression on memory B cells observed ex vivo was due to differential CXCR3 isoform expression in donors with type 1 diabetes and donors without diabetes." (PMID 41273416, 2026). "Evidence from both type 1 diabetes animal models and human pancreatic organ donors with recent-onset type 1 diabetes identified CXCL9 and CXCL10 as key chemokines that induce the attraction of autoreactive T cells bearing the corresponding chemokine receptor CXCR3 to pancreatic islets." (PMID 37458220, 2023). "To evaluate the phenotypic characteristics of naive and memory B cells in individuals with type 1 diabetes, we developed a polychromatic flow cytometry panel incorporating a viability dye and monoclonal antibodies specific for CD3, CD19, CD21, CD24, CD27, CD38, CD45R/B220, CD95, CXCR3 and IgD." (PMID 29881878, 2018). "We noted a lower expression of CXCR3 in the DN B cell subset (IgD−CD27−), in comparison with ND donors (p<0.01), a feature of this cell type that has not previously been described in type 1 diabetes." (PMID 41273416, 2026).
inflammatory bowel disease (20 papers, 2009 to 2025). A spectrum of small and large bowel inflammatory diseases of unknown etiology. "Research has demonstrated that CXCR3 expression is upregulated in celiac disease and inflammatory bowel diseases, suggesting a potential link between zonulin dysregulation and these pathological conditions." (PMID 40868118, 2025). "Reduction of CCR6 and CXCR3 in SIP T cells is in contrast to increased expression of these migration chemokines that has been reported in inflammatory bowel disease." (PMID 36825028, 2023). "The inflamed mucosa of inflammatory bowel disease (IBD) patients shows increased enrichment of CD4+CXCR3+ T cells." (PMID 35813827, 2022). "A human study of inflammatory bowel disease found that ex vivo IL-12 stimulation led to IFN-γ production in Th17 cells that were isolated as CCR6+CXCR3− cells from mesenteric lymph nodes." (PMID 32774332, 2020). "CCR5 and CXCR3 are expressed in human lamina propria lymphocytes (LPLs) and intraepithelial lymphocytes (IELs) and play important roles in recruiting leukocytes to the gut in patients with inflammatory bowel disease." (PMID 39867906, 2024). "Increased CXCR3 expression on activated T cells has been reported previously during inflammatory bowel disease (IBD), relative to controls." (PMID 35720309, 2022). "Further, it has been shown that CXCR3+ T cells increase in the lamina propria (LP) of inflammatory bowel disease (IBD) patients as compared with normal healthy donors." (PMID 29707158, 2018). "The principal targets for anti-chemokine therapy in inflammatory bowel disease (IBD) have been the receptors CCR9 and CXCR3 and their respective ligands CCL25 and CXCL10." (PMID 30137309, 2018). "CXCR3 and its ligands CXCL9, CXCL10, and CXCL11 are differentially elevated in many instances, such as with periodontal, autoimmune liver diseases, multiple sclerosis, bronchiolitis, skin or mucosal inflammation, cyclophosphamide (CYP)-induced cystitis, and inflammatory bowel disease (IBD)." (PMID 24278169, 2013).
liver fibrosis (20 papers, 2011 to 2025). "The result showed that Vγ4 cells with CXCR3 deficiency reconstituted mice (CXCR3KO) displayed significantly enhanced liver fibrosis, as assessed by H&E, Sirius Red and Masson’s Trichrome staining." (PMID 35361750, 2022). "In CXCR3-deficient mice, liver fibrosis was enhanced, and fibrosis progression was associated with a decrease in the number of intrahepatic interferon-γ-positive T cells and a reduction in interferon-γ mRNA." (PMID 34938271, 2021). "The CXCL9 pathway suppresses collagen production in LX-2 cells, and CXCR3-deficient mice also demonstrated the anti-fibrotic effect of Th1 inflammation in liver fibrosis." (PMID 31369605, 2019). "CXCL10 and its receptor CXCR3 have been implicated in fibrosis development in models of congenital hepatic fibrosis and carbon tetrachloride (CCl4)-mediated fibrosis." (PMID 31752395, 2019). "It has been suggested that the HIV infection of hepatocytes in the presence of HBV could promote inflammation and flux of CXCL10 production, thus promoting the recruitment of activated CXCR3+ cells towards the liver that could cause liver fibrosis." (PMID 36366543, 2022). "Intrahepatic mRNA for CXCL10 and CXCR3 were both strongly associated with liver fibrosis on regression analysis for TE (η2 = 0.40, p<0.001 and η2 = 0.14, p = 0.026) and liver biopsy (odds ratio 1.10 (1.04, 1.16), p = 0.001, odds ratio 3.52 (1.33, 9.26), p = 0.011)." (PMID 32898182, 2020). "In addition, intrahepatic mRNA for CXCL10 and CXCR3 were also associated with liver fibrosis and inflammation." (PMID 32898182, 2020). "However, more samples from patients at different stages of liver fibrosis are required to determine whether the levels of CXCR3-associated chemokines, particularly CXCL10, are able to serve as biomarkers of liver disease severity in HCV/HIV-1 infection." (PMID 24516541, 2014). "Given the strong anti-fibrotic potential of peripheral CXCR3(+)CD56Bright NK cells observed in healthy individuals we speculated that advanced stages of HCV-associated liver fibrosis may be associated with a decreased intra-hepatic frequency of this NK cell subset." (PMID 22792160, 2012). "In HIV and HBV co-infected patients, mRNA levels for CXCL10 and CXCR3 were correlated with liver fibrosis." (PMID 36366543, 2022). "A mouse model of liver fibrosis suggests that MyD88 signaling in activated HSCs promotes macrophage M1 polarization in a CXCL10/CXCR3-dependent manner, thus promoting liver fibrosis and inflammation." (PMID 37408838, 2022). "For instance, the overexpression of CCR1, CCR5, and CXCL4 can contribute to progression of liver fibrosis, whereas the stimulation of CXCR3 and CXCL9 exert the protective function of liver fibrosis." (PMID 35656309, 2022). "In contrast to other CXRs, the C-X-C motif receptor 3 (CXCR3) has been shown to inhibit liver fibrosis." (PMID 34938271, 2021). "Levels of intrahepatic mRNA for CXCL10 and CXCR3 correlated with liver fibrosis and immunohistochemistry demonstrated CXCL10 expression in peri-portal hepatocytes." (PMID 32898182, 2020). "Liver fibrosis (measured by both transient elastography and liver biopsy) was statistically significantly associated with intrahepatic mRNA for CXCL10 and CXCR3 using linear and logistic regression analyses adjusted for CD4 T-cell count." (PMID 32898182, 2020). "We propose a model where HIV infection of hepatocytes in the presence of HBV and local inflammation drives an increase in CXCL10, recruiting activated CXCR3+ cells to the liver; establishing a cycle of inflammation leading to liver fibrosis." (PMID 32898182, 2020). "Studies have shown that peripheral levels of CXCR3-associated chemokines, particularly CXCL10, are significantly associated with liver fibrosis in chronic HCV-infected patients." (PMID 24516541, 2014). "CXCR3 associated chemokines CXCL9 and CXCL10 were reported to be in correlation with liver fibrosis, but their roles in liver subpopulations of mice with schistosomiasis were not clear." (PMID 22905138, 2012).
liver fibrosis (continued). "Our findings indicate that targeting the mTORC2 or CXCR3 in γδ T cells could be considered as a promising approach for γδ T cell immunotherapy against liver fibrosis." (PMID 35361750, 2022). "Likewise, when compared to WT mice FFC-fed CXCR3−/− mice have reduced liver fibrosis, as assessed by Sirius red stain and mRNA expression of αSMA and collagen 1a1." (PMID 27349927, 2016). "In addition, intra-hepatic frequency of CXCR3(+) NK cells was correlated with stage of liver fibrosis (n = 15)." (PMID 22792160, 2012). "Intra-hepatic accumulation of the functionally impaired CXCR3(+)CD56Bright NK cell subset might be involved in HCV-induced liver fibrosis." (PMID 22792160, 2012). "Dys-regulated hepatic recruitment of CXCR3-expressing immunocompetent cells has been suggested as a potential mechanism involved in the observed association between levels of CXCR3 ligands and stages of HCV-induced liver fibrosis." (PMID 22792160, 2012). "Thus, we next studied intra-hepatic frequency of CXCR3(+)CD56Bright NK cells in patients showing different degrees of liver fibrosis." (PMID 22792160, 2012). "Of note, recent data indicate that the chemokines receptor CXCR3 and its ligands, especially CXCL10 (IP-10) may play an important role in the regulation of HCV-associated liver fibrosis by yet incompletely understood mechanisms." (PMID 22792160, 2012). "A strong association between CXCR3-associated chemokines CXCL9 and CXCL10 with liver fibrosis suggested that they may have promise as new non-invasive markers of liver fibrosis in HCV infected patients." (PMID 21299910, 2011). "Finally, mice lacking CXCR3 are more prone to liver fibrosis initiated by the loss of the anti-fibrogenic and angiostatic effects of CXCL9 on hepatic stellate cells and sinusoidal endothelial cells." (PMID 26731721, 2016). "In the PB of HCV+ patients with advanced liver fibrosis, there was a lower proportion of CD62L+; CD62L+/CD94++; CD27+; CD127+/CD27+ and CXCR3+/CD27+ NK subsets, as compared to patients with mild/moderate liver fibrosis." (PMID 37443584, 2023). "Meanwhile, expression of α-SMA was inhibited in LX-2 by CXCL9 but not CXCL10, suggesting the different function of CXCR3 associated chemokines in liver fibrosis and that the various chemokines might affect HSCs via non-chemokines receptors as other researchers reported." (PMID 22905138, 2012). "By binding to CXCR3, CXCL10 recruits T lymphocytes and macrophages to the liver parenchyma, promoting inflammation, apoptosis, and fibrosis through the direct induction of the proinflammatory cytokine IL-9 in a liver fibrosis model." (PMID 40977717, 2025). "Additionally, positive correlation was found between the PB CXCR3+/CD94+ NK cell percentages and intrahepatic NK cell percentages in patients with advanced hepatic fibrosis." (PMID 37443584, 2023). "Thus, IL-1β-activated mTORC2 signaling in γδ T cells upregulates CXCR3 expression, which is critical for IFN-γ+ γδ T cells migration into the liver and amelioration of liver fibrosis." (PMID 35361750, 2022).
pancreatic cancer (20 papers, 2014 to 2025). "Tumor-associated macrophages express CXCL10 in pancreatic cancer, and its acceptor CXCR3 is extremely expressed in T cells." (PMID 35685428, 2022). "Pancreatic tumor cells can also express Cxcr3, and Cxcr3:Cxcl10 interactions facilitate tumor cell migration to sensory neurons and contribute to cancer-related pain." (PMID 36472588, 2023). "The relevance of some chemokine receptors, such as CX3CR1, CXCR4, and CXCR3, has been described in pancreatic cancer." (PMID 36142575, 2022). "The CXCR4/CXCL12 axis seems to play an important role in the desmoplastic reaction characterizing PDAC, while CXCR3/CXCL10 resulted expressed in pancreatic tumor tissue, and their presence has been correlated with poor prognosis." (PMID 36142575, 2022). "Expression of both CXCL10 and CXCR3 in tumor tissue has been correlated with a poor prognosis in pancreatic cancer." (PMID 35493517, 2022). "For example, IL-35-promoted STAT3 activation, reduces the infiltration and function of CD8+ T cells in pancreatic cancer by inhibiting the expression of CXCR3, CCR5, and IFN-γ." (PMID 36291659, 2022). "Here, we delineate the importance of CXCL10/CXCR3 signaling during the early phase of murine pancreatic cancer." (PMID 34328416, 2021). "Previously, Ym1+ macrophages in the KC animal model have been shown to drive fibrosis during pancreatic cancer development, and after neutralization of CXCR3, or alternatively neutralization of CXCL10, we observed a correlating increase in fibrosis." (PMID 34328416, 2021). "Then we analyzed the RNA expression of CXCL10 and its receptor CXCR3 at single-cell level in pancreatic cancer." (PMID 34276760, 2021). "In this study, we delineate the importance of CXCL10/CXCR3 signaling during the early phase of pancreatic cancer development." (PMID 34328416, 2021). "Altogether, these data demonstrate increased expression of CXCR3 in pancreatic cancer and that CXCR3 is primarily expressed by tumor-infiltrating leukocytes." (PMID 25415223, 2014). "Our findings suggest that, in pancreatic cancer, CXCR3+ Tregs can be recruited by IP-10 expressed by PSCs in the tumor stroma, leading to immunosuppressive and tumor-promoting effects." (PMID 25415223, 2014). "We found increased M1-like macrophage accumulation in estrogen-depleted mice, where elevated CXCL10 and CCL2 levels were observed, consistent with findings in a pancreatic cancer model where CXCL10/CXCR3 signaling was shown to maintain macrophages in the pro-inflammatory M1 phenotype." (PMID 39007345, 2024). "Likewise, in vitro stimulation of pancreatic tumor cells with IFN-γ profoundly increased tumor cell production of CXCR3-specific chemokines, even in the presence of IL-6." (PMID 36881480, 2023). "Together, our results support that Cxcr3, potentially by interacting with Cxcl9/Cxc10 + cDC1s in the spleen, promotes GzmB + cytotoxic T cells that may mitigate pancreatic cancer metastasis." (PMID 36472588, 2023). "In pancreatic cancer, IP-10 induction in stroma cell could recruit CXCR3+ T lymphocyte, lead to immunosuppressive and tumor-promoting effects, and correlate with poor survival." (PMID 27448966, 2016). "Another plausible explanation for our findings is that other chemokines that bind CXCR3, present in pancreatic cancer microenvironment, may mediate migration, invasion and growth of PCCs instead of IP-10." (PMID 25415223, 2014). "High levels of IP-10 and CXCR3 have been associated with chronic pancreatitis but a role for IP-10 in pancreatic cancer has not been previously reported." (PMID 25415223, 2014). "Therefore, it is unclear if treatment of pancreatic tumors with a CXCR3 agonist will result in a polarization switch of tumor-associated macrophages that renders the lesion microenvironment less supportive for tumors, and increases efficiency of chemotherapy, or if it has a tumor-promoting effect." (PMID 34328416, 2021).